NRN1 (neuritin 1)
Diseases named in the same sentence as NRN1 in open-access papers (continued):
Sharing a sentence is not in itself a finding about the gene and the disease.
schizophrenia (5 papers, 2022 to 2025). A major psychotic disorder characterized by abnormalities in the perception or expression of reality. "Genetic association studies have revealed that a specific NRN1 haplotype (HAP678 GTT) is associated with early-onset schizophrenia, indicating a possible role in disease vulnerability." (PMID 41425077, 2025). "Included in the neurotrophins family, the Neuritin 1 gene (NRN1) has emerged as an attractive candidate gene for schizophrenia (SZ) since it has been associated with the risk for the disorder and general cognitive performance." (PMID 35806464, 2022).
Anxiety (3 papers, 2024 to 2025). Intense feelings of nervousness, tension, or panic often arise in response to interpersonal stresses. "These deficits were linked to increased anxiety and depressive-like behavior, but viral overexpression of NRN1 rescued both the structural and behavioral issues." (PMID 41425077, 2025). "This may account for higher male baseline expression of genes such as Atp1a2, Ppp3r1, and Nrn1, and a lack of an Egr1 effect on the expression of these genes and related phenotypes, such as anxiety-related behaviour, due to a possible ceiling effect in males." (PMID 41390827, 2025).
astrocytoma (3 papers, 2016 to 2017). "In cancer NRN1 acts as an angiogenic- and hypoxia-induced factor and is associated with proliferation, apoptosis, and angiogenesis of human astrocytoma." (PMID 27901477, 2017). "Up to now, only three manuscripts found a relationship between NRN1 and cancer where it was associated with angiogenesis, proliferation, and apoptosis of astrocytoma, Kaposi's Sarcoma, and cancer angiogenesis in general." (PMID 27901477, 2017). "Candidate genes include, besides others, the critical RhoA effector RTKN2 and NRN1 that is known to be associated with astrocytoma progression." (PMID 27454254, 2016). "Surprisingly, neither attachment nor proliferation are influenced by recombinant NRN1 and after knockdown of NRN1, respectively, which is in contrast to the results made in astrocytoma." (PMID 27901477, 2017). "In contrast, a molecular genetic study in astrocytomas demonstrated that overexpression of neuritin 1 correlates with proliferation, apoptosis, and angiogenesis." (PMID 27096627, 2016).
glioma (3 papers, 2020 to 2024). A benign or malignant brain and spinal cord tumor that arises from glial cells (astrocytes, oligodendrocytes, ependymal cells). "It has shown that miR-182 diminishes cell proliferation and invasion in glioma by targeting the gene encoding Neuritin protein, NRN1." (PMID 37438760, 2023). "We previously found that SPIONs can be loaded with microRNA-374a for overexpression in gliomas, thereby inhibiting the expression of endogenous NRN1 and inhibiting glioma proliferation, invasion, and tumourigenicity in nude mice." (PMID 32174801, 2020).
esophageal cancer (2 papers, 2021 to 2022). A primary or metastatic malignant neoplasm involving the esophagus. "Based on “BRCAness” principle, our recent study found that methylation of NRN1 was a novel synthetic lethal marker for PI3K-Akt-mTOR and ATR inhibitors in human esophageal cancer." (PMID 34539742, 2021).
Hyperglycemia (2 papers, 2022 to 2025). An increased concentration of glucose in the blood. "Multiple injury models, including optic nerve crush, traumatic brain injury, ischemic stroke, and hyperglycemia-induced neurotoxicity, have consistently demonstrated NRN1’s ability to reduce neuronal apoptosis." (PMID 41425077, 2025). "NRN1’s ability to counteract hyperglycemia-induced neurodegeneration, regulate apoptotic signaling, and promote structural regeneration highlights its translational promise as a therapeutic intervention." (PMID 41425077, 2025). "Then, hyperglycemia induces significant downregulation of the gene expression of Ngf and nrn1, whereas the expression of cleaved caspase-3 and NSE is significantly upregulated." (PMID 35578754, 2022).
lung carcinoma (2 papers, 2017). "Interestingly, over 80% of lung cancer specimens contained hypermethylated regions within the promoters of NRN1 and PRDM14 and at the left side of the YTHDF3 promoter." (PMID 27901495, 2017).
meningioma (2 papers, 2016). A generally slow growing tumor attached to the dura mater. "Neuritin 1 is a neurotrophic factor involved in regulating synaptic plasticity and neuronal migration and has been identified as a downregulated gene in low grade meningiomas compared to normal meninges." (PMID 27096627, 2016). "Among genes that were higher expressed in meningiomas from females were rhotekin 2 (RTKN2), neuritin 1 (NRN1), small nucleolar RNA, C/D box 114–26 (SNORD114-26), and leucine rich adaptor protein 1-like (LURAP1L)." (PMID 27096627, 2016).
mental disorder (2 papers, 2022 to 2023). A disease that has its basis in the disruption of mental process. "Consequently, inadequate Nrn1 sustenance could translate into the abnormal formation of synapses, a reduced capacity to perform adaptive responses and, in turn, a higher risk of developing a mental disorder." (PMID 35806464, 2022).
age-related hearing loss (1 paper, 2025). "Whether delivered genetically or pharmacologically, NRN1-based interventions may have future applications in preventing or slowing the progression of age-related hearing loss and ototoxicity-induced auditory damage." (PMID 41425077, 2025).
autoimmune disease (1 paper, 2024). A disorder resulting from loss of function or tissue destruction of an organ or multiple organs, arising from humoral or cellular immune responses of the individual to their own tissue constituents. "Nrn1 deficiency compromises Treg cell expansion and suppression while enhancing Te cell inflammatory response, exacerbating autoimmune disease." (PMID 39565188, 2024). "Nrn1 deficiency in mice causes dysregulation of ion channel and nutrient transporter expression in Treg and effector T cells, resulting in divergent metabolic outcomes and impacting autoimmune disease progression and recovery." (PMID 39565188, 2024). "We employed the experimental autoimmune encephalomyelitis (EAE), the murine model of multiple sclerosis (MS), to evaluate the overall impact of Nrn1 on autoimmune disease development." (PMID 39565188, 2024).
Autoimmunity (1 paper, 2024). The occurrence of an immune reaction against the organism's own cells or tissues. "Thus, the results from EAE corroborated with earlier data and confirmed the important role of Nrn1 in establishing immune tolerance and modulating autoimmunity." (PMID 39565188, 2024). "Additionally, histopathology assessment of lung, heart, liver, kidney, intestine, and spleen harvested from 13 months old Nrn1-/- and Nrn1+/- did not reveal any evidence of autoimmunity (data not shown)." (PMID 39565188, 2024).
Cognitive impairment (1 paper, 2023). Abnormal cognition is characterized by deficits in thinking, reasoning, or remembering. "The established link between synaptic loss and cognitive impairment in AD and the predominance of synaptic proteins in our top resilience-associated modules, warrants examining the impact of NRN1 on synaptic integrity and maintenance as foundational to determining NRN1’s role in resilience." (PMID 37024090, 2023).
diabetes (1 paper, 2025). "A pivotal study using a STZ-induced diabetic rat model demonstrated that diabetes markedly reduces NRN1 expression in dorsal root ganglia and sciatic nerve, which are key anatomical structures affected in peripheral neuropathy." (PMID 41425077, 2025). "Notably, treatment with NGF restored NRN1 levels in these tissues, suggesting that the neurotrophic deficit in diabetes contributes to suppressed NRN1 signaling and that upstream neurotrophins may regulate NRN1 expression." (PMID 41425077, 2025).
diabetic neuropathy (1 paper, 2025). A chronic, pathological complication associated with diabetes mellitus, where nerve damages are incurred due to diabetic microvascular injury involving small blood vessels that supply these nerves, resulting in peripheral and/or autonomic nerve dysfunction. "NRN1’s emerging profile in diabetic neuropathy expands its known function beyond the central nervous system and into the realm of peripheral nerve regeneration." (PMID 41425077, 2025).
emphysema (1 paper, 2009). "Gene expression profiling of lung from emphysema patients identified seven candidate genes associated with emphysema severity including COL6A3, SERPINF1, ZNHIT6, NEDD4, CDKN2A, NRN1 and GSTM3." (PMID 19723343, 2009). "The candidate genes (CDKN2A, GSTM3, COL6A3, SERPINF1, NRN1, NEDD4 and ZNHIT6) had ontologies that were relevant to emphysema progression, including cell cycle regulation (CDKN2A), collagen (COL6A3), anti-angiogenesis (SERPINF1) and oxidative stress (GSTM3)." (PMID 19723343, 2009).
endometriosis (1 paper, 2019). The growth of functional endometrial tissue in anatomic sites outside the uterine body. "The detailed regulatory mechanisms underlying the effect of GnRHa on NRN1 expression and the correlation between the expression of NRN1 and the pathogenesis of endometriosis require further studies." (PMID 31491902, 2019). "This study was conducted to investigate the NRN1 expressions in tissue and serum of women with endometriosis following GnRHa treatment." (PMID 31491902, 2019). "In this study, we investigated the expression of NRN1 in tissues and serum of women with endometriosis." (PMID 31491902, 2019). "Further study is needed to correlate the expression level of NRN1 and pain symptoms in women with endometriosis before and after GnRHa treatment." (PMID 31491902, 2019). "In eutopic endometrium from untreated women with endometriosis, we found an unchanged level of expression of NRN1 both in the proliferative and secretory phases." (PMID 31491902, 2019). "It suggests that NRN1 may be a potential biomarker reflecting the therapeutic efficacy of GnRHa treatment for endometriosis." (PMID 31491902, 2019). "Considering the cyclical nature of the endometrium and the fact that endometriosis is an estrogen-dependent disease, we also studied whether the menstrual cycle affects the expression of NRN1." (PMID 31491902, 2019). "Decreased expression levels of NRN1 was observed in both endometrial glands’ epithelial and stromal cells in eutopic endometrium and endometriotic tissues of women with endometriosis who received GnRHa treatment." (PMID 31491902, 2019). "A complementary DNA (cDNA) microarray study showed that the neuritin 1 (NRN1) gene is upregulated in the ectopic endometrium of women with endometriosis, which suggests that NRN1 may be associated with this disease." (PMID 31491902, 2019). "However, the effect of hormonal treatment on NRN1 expression in women with endometriosis needs to be elucidated." (PMID 31491902, 2019). "There is evidence that a gonadal steroid induced the expression of NRN1 in the motor neuron, whereas the question of how estradiol may induce NRN1 expression in endometriosis needs further investigation." (PMID 31491902, 2019). "In contrast, increased expression of NRN1 was found in the epithelial cells of the endometrial glands and stroma cells during both the proliferative and secretory phases in eutopic endometrium of the untreated women with endometriosis." (PMID 31491902, 2019). "Both epithelial and stromal cells of endometriotic tissues from untreated women with endometriosis exhibited stronger staining of NRN1 but not in those who were treated with GnRHa." (PMID 31491902, 2019). "Likewise, the menstrual cycle did not affect the NRN1, mRNA and protein levels (in endometriotic tissues and serum) of women with endometriosis." (PMID 31491902, 2019).
germ cell tumor (1 paper, 2021). A benign or malignant, gonadal or extragonadal neoplasm that originates from germ cells. "Because we previously identified that NRN1 was abundantly expressed in patient-derived testicular germ cell tumor spheroid cultures with the enrichment of cancer stemness characteristics, we particularly examined the co-expression of NRN1 with stemness-related genes in RCC." (PMID 34804954, 2021).
glaucoma (1 paper, 2025). Increased pressure in the eyeball due to obstruction of the outflow of aqueous humor. "While glaucoma represents the primary target for NRN1-based therapeutics in ophthalmology, its broad neuroprotective effects imply potential applications across the spectrum of optic neuropathies." (PMID 41425077, 2025). "The overall evidence presented positions NRN1 as a transformative therapeutic opportunity in glaucoma and other neurodegenerative disease management, representing a shift from purely pressure-based interventions to comprehensive neuroprotective strategies." (PMID 41425077, 2025). "Collectively, these results support the therapeutic potential of NRN1 as a neuroprotective agent in glaucoma." (PMID 41425077, 2025). "In both optic nerve injury and glaucoma models, NRN1 has demonstrated the capacity to support the survival of RGCs and their neurite outgrowth, highlighting its therapeutic relevance." (PMID 41425077, 2025). "Within this emerging therapeutic landscape, NRN1 has garnered attention for its potential role as a novel neurotrophic factor with applications in glaucoma." (PMID 41425077, 2025). "NRN1 is being explored as a potential therapy across specialties through leveraging its mechanistic processes to hinder the driving pathophysiological forces behind clinical conditions such as glaucoma, AD, and stroke." (PMID 41425077, 2025). "Particularly compelling is NRN1’s demonstrated efficacy in the sophisticated TAS model, which replicates the pressure differentials characteristic of glaucoma using human donor eyes." (PMID 41425077, 2025). "NRN1 is uniquely positioned as it can target multiple pathophysiological drivers of glaucoma, including lack of neurotrophic support and aberrant intracellular signaling, ultimately addressing the critical endpoint of glaucoma’s pathophysiological process: the loss of RGCs." (PMID 41425077, 2025).
gynecological cancers (1 paper, 2019). "Whether AMPD3/NRN1/TBX15 methylations may occur in other gynecological cancers or in benign tumors remains to be determined." (PMID 31775891, 2019).
hereditary optic neuropathies (1 paper, 2025). "Conditions such as anterior ischemic, traumatic, and hereditary optic neuropathies share RGC injury pathways that could benefit from NRN1." (PMID 41425077, 2025).
ischemic stroke (1 paper, 2025). A stroke disorder caused by obstruction of blood flow to the brain, due to thrombotic (local blood clot formation) or embolic (due to a blood clot or other material traveling from another site) event. "In models of ischemic stroke, particularly those involving middle cerebral artery occlusion, NRN1 shows significant neuroprotective properties." (PMID 41425077, 2025). "In both hemorrhagic and ischemic stroke, emerging data position NRN1 as a promising neuroprotective agent due to its multifaceted role in supporting synaptic function, reducing neuroinflammation, and enhancing tissue integrity." (PMID 41425077, 2025).
lymph node metastasis (1 paper, 2021). "Furthermore, our pathological analysis demonstrated that NRN1 high immunoreactivity tended to correlated with lymph node metastasis and distant metastasis." (PMID 34804954, 2021).
neuritis (1 paper, 2019). A neuropathy arising from inflammation of one or more nerves. "Nrn1 can stimulate rapid growth and branching of neuritis, which plays an important role in regeneration and repair after the nervous system is damaged." (PMID 31010100, 2019).
optic neuropathies (1 paper, 2025). "Nevertheless, the accumulating evidence situates NRN1 at the intersection of molecular neuroprotection and translational ophthalmology, offering hope for novel strategies to preserve vision in patients at risk of progressive optic neuropathies." (PMID 41425077, 2025). "Overall, the accumulating evidence positions NRN1 at the intersection of molecular neuroprotection and translational ophthalmology, offering hope for novel strategies to preserve and potentially restore vision in patients at risk of progressive optic neuropathies." (PMID 41425077, 2025).
ovarian carcinoma (1 paper, 2019). A malignant neoplasm originating from the surface ovarian epithelium. "Ovarian cancer detection from cervical scrapings is feasible, using particularly promising epigenetic biomarkers such as AMPD3/NRN1/TBX15." (PMID 31775891, 2019).
ovarian endometriosis (1 paper, 2019). A non-neoplastic disorder characterized by the growth of endometrial tissue in the ovaries. "This study aimed to investigate the effect of gonadotropin-releasing hormone agonist (GnRHa) treatment on the expression of neuritin 1 (NRN1) in women with ovarian endometriosis." (PMID 31491902, 2019). "The expression of NRN1 was significantly lower in women with ovarian endometriosis treated with GnRHa." (PMID 31491902, 2019). "Our study showed that GnRHa treatment could also reduce the expression of neurotrophic factor, NRN1 in patients with ovarian endometriosis." (PMID 31491902, 2019).
psychosis (1 paper, 2022). "Nevertheless, further functional data on these SNPs are needed to fully characterise their impact on the underlying mechanisms that connect NRN1 and age at onset of psychosis." (PMID 35806464, 2022). "Furthermore, they suggest that these prefrontal networks of sustained activation during WM, in which NRN1 appears to have a relevant role, might be especially sensitive to the earlier onset of psychosis." (PMID 35806464, 2022).
Stroke (1 paper, 2025). Sudden impairment of blood flow to a part of the brain due to occlusion or rupture of an artery to the brain. "Their results also showed that higher circulating NRN1 levels correlated with increased hematoma volume, more severe neurological deficits at presentation, and worse outcomes at 90 days post-stroke." (PMID 41425077, 2025). "Taken together, these preclinical and clinical findings position NRN1 as a multipotent neuroprotective factor in stroke." (PMID 41425077, 2025). "NRN1’s neuroprotective properties can play a role in stroke treatment." (PMID 41425077, 2025). "With NRN1’s remarkable ability to reduce infarct size and shift the inflammatory microenvironment, future research should continue to investigate NRN1’s ability to optimize the neural cytokine profile and ameliorate neuroinflammation to enhance stroke recovery." (PMID 41425077, 2025). "Furthermore, future studies should focus on NRN1 as a potential mediator of improving and restoring cognition and function post-stroke." (PMID 41425077, 2025). "Consequently, NRN1 may serve as a biomarker for stroke severity and a potential predictor of long-term prognosis, although its precise pathophysiologic and diagnostic roles require further investigation." (PMID 41425077, 2025).
testicular germ cell tumor (1 paper, 2021). A germ cell tumor arising from the testis. "We recently characterized that neuritogenesis-related protein neuritin 1 (NRN1) functions as an oncogene in testicular germ cell tumor." (PMID 34804954, 2021). "We recently demonstrated that neuritogenesis-related protein neuritin 1 (NRN1) can be a potential therapeutic target in testicular germ cell tumor (TGCT) under the regulation by HIF1α." (PMID 34804954, 2021). "We have previously showed that NRN1 is abundantly expressed in testicular germ cell tumor PDC spheroid culture, and NRN1 expression is transcriptionally regulated by hypoxia inducible factor 1α (HIF1α)." (PMID 34804954, 2021).
urothelial carcinoma (1 paper, 2025). A malignant neoplasm derived from the transitional epithelium of the urinary tract (urinary bladder, ureter, urethra, or renal pelvis). "In order to develop the methylation assay for detecting urothelial carcinoma, we conducted a screening of 14 CpG sites in 7 genes (HIST1H4F, SOX1-OT, Vim, Onecut2, Twist1, NRN1, POU4F2) based on the literature review." (PMID 40855090, 2025).